MYC (MYC proto-oncogene, bHLH transcription factor)
Diseases named in the same sentence as MYC in open-access papers (continued):
Sharing a sentence is not in itself a finding about the gene and the disease.
bladder cancer (continued). "As such, the METTL3/AFF4/MYC axis contributes to bladder cancer tumorigenesis." (PMID 34185971, 2022). "Similarly, the MYC protein levels were selectively inhibited markedly in bladder cancer 5637 and T24 cells except HFF." (PMID 33816560, 2021). "Moreover, cells with increased expression of MYC genes were susceptible to Oxaliplatin, which had been approved by FDA for bladder cancer." (PMID 34692520, 2021). "MYC is an oncogene in bladder cancer and crRNA was designed to target MYC." (PMID 33816560, 2021). "In bladder cancer, circCDYL suppresses c-MYC to reduce cell proliferation and migration." (PMID 34258296, 2021). "This m6A-regulated malignant regulatory network effectively increases MYC protein levels in bladder cancer and may lead to difficulties in reducing MYC by blocking a single signaling pathway." (PMID 32765970, 2020). "CircCDYL has been suggested to suppress cell growth by inhibiting MYC protein expression levels in bladder cancer through an unknown mechanism." (PMID 33287884, 2020). "They further found that methyltransferase-like 3 (METTL3), an main component in the so-called m6A ‘writer’, could promote bladder cancer progression via AFF4/NF-κB/MYC signaling network by an m6A dependent manner." (PMID 31228940, 2019). "In bladder cancer, METTL3 could promote the bladder cancer progression via AFF4/NF-κB/MYC signaling network by an m6A dependent manner." (PMID 31228940, 2019). "In addition to FGFR3, alterations in a number of other genes including MYC and CCND1 (encoding cyclin D1), are found in bladder cancers and thought to contribute to oncogenesis." (PMID 29423038, 2018). "Additionally, the enrichment in active chromatin in the identified enhancer region was found to be similar to the c-MYC promoter region, supporting its potential regulatory activity in bladder cancer cells." (PMID 29956121, 2018). "This regulation of FGFR3 by MYC seemed to be quite specific to bladder cancer, because MYC binding to the FGFR3 enhancers or promoter was rarely observed in a publicly available dataset encompassing 118 MYC chromatin immunoprecipitation and sequencing (ChIP‐Seq) in different tissues." (PMID 29463565, 2018). "Then, we constructed tandem amiRNA sequences targeting oncogenic MYC in bladder cancer driven by UAS and tested whether synthetic regulatory RNAs can regulate the expression of amiRNA." (PMID 29084575, 2017). "Interestingly, hierarchical clustering showed an association of p63 with luminal markers in UTUC although p63 usually controls MYC expression in human bladder cancer cells, which is enriched in basal tumors." (PMID 28632777, 2017). "Many protein coding genes from the newly identified ceRNA network were reported as oncogenes and/or tumor suppressors participating in bladder cancer development and progression, such as CDKN1A, HMGA2 and MYC, which also was considered as promising therapeutic targets for bladder cancer." (PMID 27863388, 2016). "High levels of MYC lead to low survival in bladder cancer (BLCA)." (PMID 27366943, 2016). "The findings suggest the importance of MYC to the malignant phenotype of bladder cancer cells." (PMID 16749926, 2006). "Therefore, we aimed to test whether MYC and/or NFKB are associated with progression in bladder cancer." (PMID 40026699, 2025). "In addition, an existing study indicated that the methylation enzyme METTL3 could increase the MYC expression by performing m6A modification of the MYC mRNA in bladder cancer." (PMID 33048840, 2020). "Additionally, functional experiments showed that MYC is an oncogene in bladder cancer cells." (PMID 29084575, 2017). "Thus, we can use this strategy to control the expression of MYC in bladder cancer cells." (PMID 29084575, 2017).
bladder cancer (continued). "Thus, future studies elucidating the role of MYC and rs9642880 in bladder cancer may have an impact on the selection of patients who may benefit from MYC-targeted therapies." (PMID 23752272, 2013). "We developed a Risk Score model that was related to the overall survival of bladder cancer patients based on doxorubicin-target HRGs: ACTG2, MYC, PDGFRB, DHRS2, and KLRD1." (PMID 38806990, 2025). "A mechanistic study reveals that RBPMS suppresses bladder cancer cell migration by regulating alternative splicing of ANKRD10, which modulates MYC pathway activity through ANKRD10-2’s function as a transcriptional coactivator." (PMID 40044952, 2025). "In bladder cancer, POLD1 stabilizes MYC by inhibiting its degradation via FBXW7, promoting proliferation and metastasis." (PMID 40661943, 2025). "PTPN12 depletion (shPTPN12) in the weakly metastatic breast and bladder cancer lines (UMUC3) increased ES-TF expression whereas PTPN12 transduction in 1833 decreased NANOG, MYC, and SOX2 expression." (PMID 38886396, 2024). "In contrast, other studies involving cell lines of bladder cancer and other cancers have described the predominant role of ERK pathway in regulating MYC protein levels." (PMID 39031286, 2024). "In bladder cancer, SNHG3 regulates c-MYC to stabilize BMI1 mRNA, highlighting its role in tumorigenesis and proposing the SNHG3/c-MYC/BMI1 axis as a novel therapeutic target." (PMID 39349640, 2024). "Our results reveal that the expression levels of stemness (SOX2, c-MYC, Nanog, and OCT4) and EMT (N-cadherin) markers are positively correlated with the cisplatin resistance development of bladder cancer cells." (PMID 38139437, 2023). "IRF5 (p=0.055), CCN1 (p=4.1e-08), MYC (p=0.039), POU5F1 (p=0.027), and TGFB1I1 (p=6.5e-08) were significantly differentially expressed at different stages of bladder cancer." (PMID 37433010, 2023). "In bladder cancer, this RBP usually promotes tumor proliferation, migration, and invasion by regulating the expression of MYC and FSCN1." (PMID 37835380, 2023). "LIN28B can also promote the expression of MYC through the LIN28B/let-7a pathway and promote the proliferation, invasion, and metastasis of bladder cancer cells." (PMID 36831493, 2023). "M6A readers (YTHDF2, IGF2BP1, and IGF2BP3) promote the progression of bladder cancer by stabilizing SETD7, KLF4, FSCN1, and MYC mRNA and regulating JAK/STAT signaling pathway activation." (PMID 35945641, 2022). "Recent studies showed that METTL3-mediated m6A hypermethylation promotes the progression of bladder cancer by regulating SETD7/KLF4 mRNA expression, pri-mrR221/222 maturation and AFE4/NF-κB/MYC signaling network activation." (PMID 35945641, 2022). "METTL3 can also promote the progression of bladder cancer through both the NF-κB and MYC signaling networks since AFF4, IKBKB, and p65 as well as MYC transcripts are methylated and stabilized by METTL3." (PMID 36008936, 2022). "In bladder cancer, METTL3 mediates the m6A modification of the AFF4 gene, which binds to the promoter of MYC and elevates MYC expression to promote cancer progression." (PMID 34315512, 2021). "Cheng et al31 found that the expression of METTL3 was elevated in bladder cancer and further identified AF4/FMR2 family member 4 (AFF4), key regulators of the NF‐κB pathway (IKBKB and RELA) and MYC as direct downstream targets of METTL3." (PMID 32808488, 2020). "In bladder cancer, METTL3 regulates methylation of MYC as well as two specific factors in the nuclear factor-kappaB (NF-κB) pathway to stimulate the overall tumorigenesis." (PMID 33048840, 2020). "Intriguingly, glucose supplementation completely restored c-MYC expression, abrogated AMPK pathway activation and markedly rescued bladder cancer cells from autophagic cell death." (PMID 32382009, 2020).
bladder cancer (continued). "Our data therefore identify MYC as a master regulator of proliferation activated downstream from FGFR3 and as a positive regulator of FGFR3 expression in bladder cancer lines." (PMID 29463565, 2018). "Our results demonstrated that when cells express iRNA and GAL4-VP64 protein in bladder cancer cells and HFF cells, the expression of MYC cannot be significantly inhibited." (PMID 29084575, 2017). "Hyperglycemia upregulates HK2 and promotes its nuclear localization in bladder cancer cells, where nuclear HK2 forms a complex with MYC to co-activate HK2 and LDHA transcription, thereby enhancing glycolysis, stemness, and tumor growth in hyperglycemic conditions." (PMID 41951587, 2026). "In colorectal cancer (CRC) and bladder cancer (BC), METTL3 accelerates the cell cycle of tumor cells by directly promoting the expressions of CCNE1, AF4/FMR2 family member 4 (AFF4), two key regulators of the NF-κB pathway (IKBKB and RELA), and MYC." (PMID 40136363, 2025). "In bladder cancer, POLD1’s stabilization of MYC suggests that MYC inhibitors (e.g., KJ-Pyr-9) could disrupt this axis, while miR-155 agonists might suppress POLD1 expression by downregulating FOXO3a, reducing replication fidelity in tumor cells." (PMID 40661943, 2025). "It will be crucial to investigate MYC alterations in FGFR3 aberrant urothelial bladder cancer, as it may provide further insight into the pathogenesis of bladder cancer, and it could also have therapeutic implications." (PMID 39031286, 2024). "Studies have shown that the antitumor effects of FGFR inhibition in FGFR3 dependent bladder cancer cells and other FGFR dependent cancers may be mediated through c-MYC, a key downstream effector of activated FGFR that is involved tumorigenesis." (PMID 39031286, 2024). "POLD1, one of the four subunits of DNA polymerase δ (POLD1, POLD2, POLD3, and POLD4) and which is upregulated in many tumors including bladder cancer, has been shown to directly bind to MB1 domain of MYC competitively with Fbw7, preventing Fbw7-mediated MYC ubiquitination and degradation." (PMID 39031286, 2024). "CircCDYL, which is derived from the exon 4 of CDYL through back splicing, inhibits bladder cancer cell growth by down regulating the protein level of MYC without altering mRNA level of MYC." (PMID 39031286, 2024). "The MYC transcription factor has been shown to be a key downstream effector of FGFR signaling, mediating tumorigenicity in different FGFR aberrant cancer cells including bladder cancer." (PMID 39031286, 2024). "Similarly, in TCGA database bladder cancer samples, CCN1 (p=7.9e-07), MYC (p=0.0043), POU5F1 (p=0.021), and TGFB1I1 (p=6.0e-05) had significant differences in bladder cancer high-grade and low-grade samples, in addition to IRF5 (p=0.2)." (PMID 37433010, 2023). "In preliminary studies, we found that the expression levels of the classic proto-oncogenes, IGF2BP1, MYC, LIN28B and STAT3 in bladder cancer T24 cells were higher than those in normal cells, while the expression levels of the tumor suppressor genes FTO and TIA1 were negligible in T24 cells." (PMID 35288535, 2022). "In short, the mRNA and protein levels of MYC were restrained selectively in bladder cancer without affecting normal cells via engineered CRISPR/Cas13d sensing hTERT." (PMID 33816560, 2021). "Because factors in ESC signaling and iPSC reprogramming have been linked to tumor malignancy, we used the Cox’s proportional hazards model to analyze the link between SOX2, KLF4, MYC and OCT4 expression and recurrence-free survival outcome for bladder cancer patients." (PMID 32427884, 2020). "Besides, AFF4 binds to the promoter of MYC, suggesting the METTL3/m6A/AFF4/NF-κB/MYC axis for bladder cancer tumorigenesis." (PMID 33099572, 2020).
bladder cancer (continued). "We found that SOX2, but not OCT4, KLF4, or MYC expression, correlates with poor prognosis and histologic differentiation in bladder cancer." (PMID 32427884, 2020). "This study further explored the mechanism of the ERH gene in the metastasis of the T24 human bladder cancer cell line and found that ERH may regulate MYC gene expression." (PMID 30866868, 2019). "The FGFR3/MYC positive feedback loop involving p38 and AKT activation by FGFR3 identified in bladder cancer cell lines may, therefore, also occur in human bladder tumors with genetic alterations of FGFR3." (PMID 29463565, 2018). "Without the aRNA, mRNA and protein levels of MYC, cell growth, cell apoptosis and cell migration were no significance in two bladder cancer cell lines, T24 and 5637, and human foreskin fibroblast (HFF) cells." (PMID 29084575, 2017). "The subsequently elevated levels of MYC increases the transcription of POLD1 forming a positive feedback loop, and it was suggested that this non-enzymatic function of POLD1 may play a role in the tumorigenesis and progression of bladder cancer." (PMID 39031286, 2024). "We also showed that MYC upregulated FGFR3 expression directly, by binding to enhancers upstream from FGFR3, as part of a FGFR3/MYC positive feedback loop operating both in vitro and in vivo in bladder cancer‐derived cell lines xenografts and in a PDX model bearing an FGFR3 mutation." (PMID 29463565, 2018). "Here, the authors report a non-canonical role of POLD1 wherein it stabilises MYC protein, creating a positive feedback loop with POLD1 expression and driving bladder cancer progression and metastasis." (PMID 37105989, 2023). "However, other studies have reported that the FUBP1-MYC axis might not be ubiquitous since MYC expression is not altered by FUBP1 silencing in different cell types, such as normal fibroblasts, prostate and bladder cancer." (PMID 32481602, 2020).
lung adenocarcinoma (179 papers, 2008 to 2026). A carcinoma that arises from the lung and is characterized by the presence of malignant glandular epithelial cells. "MYC amplification correlates with poor prognosis in early-stage lung adenocarcinoma and is observed in 6%–25% of SCLC cases, linked to reduced survival and therapy resistance." (PMID 41353695, 2025). "Mutations in the MYC transcription factor network tumor suppressor gene MGA were previously identified as inactivating mutations in 10% of lung adenocarcinomas." (PMID 39052387, 2024). "We observed an increase in the expression of MYC following the loss of UBQLN1 or UBQLN2 in lung adenocarcinoma cell lines including A549, HOP62, H23, and H2009." (PMID 37444499, 2023). "We further confirmed our findings of stabilization of MYC following the loss of UBQLN1 in additional lung adenocarcinoma cell lines PC9 and H358." (PMID 37444499, 2023). "Next, we performed immunofluorescence staining of MYC in lung adenocarcinoma cell lines following a loss of UBQLN1 or UBQLN2." (PMID 37444499, 2023). "In our study using lung adenocarcinoma cell lines, we observed an increase in the expression of MYC following the loss of either UBQLN1 and/or UBQLN2." (PMID 37444499, 2023). "We observed an increase in the expression of MYC following the loss of UBQLN1 in the lung adenocarcinoma cell line." (PMID 37444499, 2023). "MYC, a transcription regulator associated with the stemness of cancer cells, is overexpressed in lung adenocarcinoma." (PMID 35433477, 2022). "MGA is significantly mutated in lung adenocarcinoma and participates in the negative regulation of MYC." (PMID 35223840, 2022). "Loss-of-function MGA mutations with MYC amplification in lung adenocarcinoma have been newly described and MGA gene was identified by SomInaClust analysis in our study." (PMID 32998690, 2020). "Taken together, we conclude that in the context of c-MYC-driven lymphomagenesis or mutant KrasG12D-driven lung adenocarcinoma development, additional co-occurring mutations are required to resolve Zmat3 tumor suppressive activity." (PMID 33082333, 2020). "Moreover, MYC+ lung adenocarcinoma showed a poor outcome and had higher risk of transformation to small-cell lung cancer." (PMID 40615564, 2025). "Interestingly, we observed that MYC was significantly upregulated following the loss of UBQLN1 in lung adenocarcinoma cell lines." (PMID 37444499, 2023). "We observed an increase in cell viability and clonogenic potential following the loss of either UBQLN1 or UBQLN2 in lung adenocarcinoma cells, which we hypothesized was due, at least in part, to increased MYC expression." (PMID 37444499, 2023). "Importantly, simultaneous LKB1 and KRAS mutations in lung adenocarcinoma cell lines were previously shown to prevent MYC downregulation and sensitivity in response to BET inhibition." (PMID 29721157, 2018). "Furthermore, a recent study showed that the MZF1 (Myeloid Zinc Finger 1)/c-MYC axis is essential for progression of lung adenocarcinomas; it is mediated by the cellular loss of the wild-type liver kinase B1 gene, i.e. a tumor suppressor frequently repressed in the pathogenesis of epithelial cancers." (PMID 26427040, 2015). "As a case study, we analyzed the MYC locus (chr8: 127,200,000–127,750,000 bp) in Calu3 lung adenocarcinoma cells, which exhibit high MYC expression." (PMID 41251144, 2026). "Our previous research demonstrated the proliferation and immune regulation of FGL1 in tumors, which indicated that FGL1 downregulation inhibits lung adenocarcinoma cell proliferation via MYC signaling." (PMID 41024301, 2025). "In contrast to lung adenocarcinoma, survival analysis of the TCGA lung squamous cell carcinoma (LUSC) dataset revealed that the expression levels of BIRC3, CXCL5, DKK1, FOSL1, and MYC exhibited limited association with patient survival." (PMID 39858622, 2025).